B4GALNT3 (beta-1,4-N-acetyl-galactosaminyltransferase 3)
Description:
Transfers N-acetylgalactosamine (GalNAc) from UDP-GalNAc to N-acetylglucosamine-beta-benzyl with a beta-1,4-linkage to form N,N'-diacetyllactosediamine, GalNAc-beta-1,4-GlcNAc structures in N-linked glycans and probably O-linked glycans. Mediates the N,N'-diacetyllactosediamine formation on gastric mucosa.
Synonyms: B4GalNac-T3; FLJ16224; FLJ40362
Tractability: Antibody: UniProt predicts a signal peptide or a membrane-spanning region.
Gene: Protein-coding gene on chromosome 12 (459,923 to 563,509, forward strand). Ensembl gene ENSG00000139044.
Subcellular location: Golgi apparatus, Golgi stack membrane
Subcellular location (Human Protein Atlas): Golgi apparatus; Vesicles
Gene Ontology:
Molecular function: acetylgalactosaminyltransferase activity; N-acetyl-beta-glucosaminyl-derivative 4-beta-N-acetylgalactosaminyltransferase activity
Cellular component: Golgi apparatus; Golgi cisterna membrane
Genetic constraint (gnomAD): Loss-of-function variants: 87 observed, 124.58 expected, observed/expected ratio (o/e) 0.7, 90% interval 0.59 to 0.83. The upper end of that interval is the gene's LOEUF score, 0.83, which puts it in group 3 of 6, group 1 being the genes least tolerant of losing a copy. Missense variants: 1,166 observed, 1,319.9 expected, observed/expected ratio (o/e) 0.88, 90% interval 0.84 to 0.93. Synonymous variants: 518 observed, 515.38 expected, observed/expected ratio (o/e) 1.01, 90% interval 0.93 to 1.08.
Homologues: Orthologues: macaque B4GALNT3 (93% identical), chimpanzee B4GALNT3 (93% identical), dog B4GALNT3 (88% identical), rabbit B4GALNT3 (87% identical), pig B4GALNT3 (85% identical), mouse B4galnt3 (83% identical), rat B4galnt3 (82% identical), guinea pig B4GALNT3 (80% identical), tropical clawed frog b4galnt3 (48% identical), zebrafish b4galnt3b (45% identical), zebrafish b4galnt3a (33% identical). Paralogues in human: B4GALNT4 (45% identical), CHSY3 (15% identical), CHSY1 (14% identical), CHPF2 (12% identical), CSGALNACT1 (11% identical), CHPF (10% identical), CSGALNACT2 (10% identical).
Diseases named in the same sentence as B4GALNT3 in open-access papers:
B4GALNT3 is named in the same sentence as 15 diseases in open-access papers, as found by Europe PMC text mining. Sharing a sentence is not in itself a finding about the gene and the disease. The quoted sentences say what the papers report.
colon cancer (8 papers, 2014 to 2022). "B4GALNT3 overexpression significantly promotes malignant behaviors of colon cancer cells both in vitro and in vivo through enhanced mitogen-activated protein kinase (MAPK) signaling pathways." (PMID 27686492, 2016). "B4GALNT3 can act both as tumor suppressor in neuroblastoma and as oncogene in the colon, increasing the malignant phenotype of colon cancer cells through enhanced integrin and MAPK signaling." (PMID 25803323, 2015). "We previously showed that B4GALNT3 overexpression enhances colon cancer cell malignant phenotypes in vitro and in vivo." (PMID 25003232, 2014). "We also found that B4GALNT3 plays an important role in regulating the colon cancer stem-like cell property by modulating the LacdiNAc structure on EGFR." (PMID 25003232, 2014). "Our previous study showed that overexpression of B4GALNT3 enhances malignant phenotypes of colon cancer cells and increases tumor growth in a mouse xenograft model." (PMID 25003232, 2014). "In our previous study, we found that B4GALNT3 overexpression enhances malignant phenotypes of colon cancer cells in vitro, and increases tumor growth and metastasis in vivo." (PMID 25003232, 2014). "Taken together, these data suggest B4GALNT3 regulates cancer stemness and the invasive properties of colon cancer cells through modifying EGFR glycosylation and signaling." (PMID 25003232, 2014). "Since colon cancer cell lines used in this study harbored either different KRAS or BRAF mutation, our results suggest that B4GALNT3 knockdown suppressed cell malignant phenotype and cancer cell stemness irrelevantly to the status of KRAS and BRAF." (PMID 25003232, 2014). "Moreover, cell line experiments revealed that B4GALNT3 expression regulates cancer stemness and the invasive properties of colon cancer cells through modifying epidermal growth factor receptor (EGFR) glycosylation and downstream signaling." (PMID 27686492, 2016). "However, in human colon cancers, our research team previously presented that B4GALNT3 messenger RNA (mRNA) is frequently up-regulated in primary colon cancer tumors compared with their normal counterparts." (PMID 27686492, 2016). "Our result showed that B4GALNT3 knockdown reduced LacdiNAc structure on EGFR in colon cancer cells." (PMID 25003232, 2014). "Our data suggest that B4GALNT3 is able to regulate the stem-like property of colon cancer cells." (PMID 25003232, 2014). "We therefore investigated whether B4GALNT3 could regulate stem-like potential of colon cancer cells via the EGF/EGFR pathway." (PMID 25003232, 2014). "Certain parts of “Region 2” of HBV genotype D were found within the intronic region of Beta-1,4-N-acetyl-galactosaminyl transferase 3 (B4GALNT3), which was shown to be overexpressed in colon cancer cells regulating the stemness." (PMID 36556285, 2022). "Our data showed that several glycoproteins in colon cancer cells can be bound by WFA lectin, and B4GALNT3 modifies the LacdiNAc on these molecules although p170 is the predominant one." (PMID 25003232, 2014). "In this study, we first showed that B4GALNT3 modulates the LacdiNAc on EGFR, influences its activity and signaling in colon cancer cells, and in turn alters cancer stemness property." (PMID 25003232, 2014). "B4GALNT3 knockdown suppresses EGF-induced sphere formation, migration and invasion of colon cancer cells." (PMID 25003232, 2014). "We have demonstrated for the first time that B4GALNT3 can regulate cancer stem cell properties via modifying EGFR glycosylation and signaling in colon cancer cells." (PMID 25003232, 2014). "B4GALNT3 knockdown did not alter bFGF-induced sphere formation in colon cancer cells." (PMID 25003232, 2014).
colorectal cancer (3 papers, 2014 to 2017). A primary or metastatic malignant neoplasm that affects the colon or rectum. "In this study, we found that B4GALNT3 is upregulated in advanced stages colorectal cancer and associated with poor prognosis." (PMID 25003232, 2014). "Our results indicate B4GALNT3 as a marker of poor prognosis of colorectal cancer and suggest a metastasis-promoting function of the glycosyltransferase in colorectal cancer." (PMID 25003232, 2014). "Our findings not only provide novel insights into the significant role of LacdiNAc in colorectal cancer stemness and but also suggest B4GALNT3 as a potential therapeutic target." (PMID 25003232, 2014). "Statistical results from immunohistochemistry of different stage of colorectal cancers showed that B4GALNT3 overexpression was observed in 18.18% (2/11) of stage I colorectal cancer and in 33.33% (5/15) of stage II colonrectal cancer." (PMID 25003232, 2014). "We found that B4GALNT3 expression was positively correlated with advanced stages and poor survival in colorectal cancer patients." (PMID 25003232, 2014). "However, the same research team has recently published that B4GALNT3 overexpression in colorectal cancer cells suppressed cell migration, invasion, and adhesion, while B4GALNT3 knockdown enhanced malignant cell phenotypes promoting cell migration and invasion." (PMID 24904828, 2014). "This raises the possibility that regulation on B4GALNT3 expression may be crucial for tumor progression of colorectal cancer." (PMID 25003232, 2014). "Here, we further demonstrated that B4GALNT3 is upregulated in advanced stages of colorectal cancer." (PMID 25003232, 2014). "This study also suggests that targeting B4GALNT3 or LacdiNAc may be a promising strategy to suppress or eliminate cancer stem cells in colorectal cancer." (PMID 25003232, 2014). "In conclusion, we showed that B4GALNT3 is overexpressed in advanced stages colorectal cancer." (PMID 25003232, 2014). "There was a higher percentage of B4GALNT3 overexpression in 73.33% (11/15) of stage III colorectal cancer and in 60.00% (9/15) stage IV colorectal cancer." (PMID 25003232, 2014).
papillary thyroid carcinoma (2 papers, 2015 to 2016). "In a recent report on papillary thyroid carcinoma (PTC), WNK1-B4GALNT3 fusion was correlated with the overexpression of B4GALNT3." (PMID 27322213, 2016).
atherosclerosis (1 paper, 2023). A disease characterized by the build-up of fatty material and calcium deposition in the arterial wall resulting in partial or complete occlusion of the arterial lumen. "We considered the SOST cis variant and B4GALNT3, SERPINA1, and RIN3 trans variants identified above as possible instruments for MR analyses of the effect of lower sclerostin levels on atherosclerosis risk." (PMID 37096546, 2023).
Colorectal Tumors (1 paper, 2014). "Chi-square test showed that B4GALNT3 overexpression in colorectal tumors is positively associated with advanced American Joint Committee on Cancer stages (p = 0.01918) by immunohistochemical stain." (PMID 25003232, 2014). "Representative images of immunohistochemistry showed B4GALNT3 expression in different stage of colorectal tumors compared with their surrounding non-tumorous tissues." (PMID 25003232, 2014).
glioma (1 paper, 2025). A benign or malignant brain and spinal cord tumor that arises from glial cells (astrocytes, oligodendrocytes, ependymal cells). "Five genes (KIF5C, LINC00632, B4GALNT3, HIF3A, and RAD51L3-RFFL) show significant differential expression between primary and recurrent tumors, with four having established functional roles in glioma pathobiology." (PMID 41356219, 2025). "The identification of five genes (KIF5C, LINC00632, B4GALNT3, HIF3A, and RAD51L3-RFFL) with differential expression between primary and recurrent tumors provides critical insight into the molecular mechanisms driving recurrence, the key challenge in the management of IDH wild-type glioma." (PMID 41356219, 2025).
ovarian carcinoma (1 paper, 2017). A malignant neoplasm originating from the surface ovarian epithelium. "Interestingly, two of the four possible β1‐4‐acetylgalactosamine transferase genes (B4GALNT1‐4), B4GALNT3 and B4GALNT4, were found to be significantly elevated (P < 0.05) in the ovarian cancer tissues as compared to the peritoneum." (PMID 28853212, 2017).
pancreatic cancer (1 paper, 2020). "After the multi-step validation, we identified B3GNT3, B4GALNT3, FUT3, FUT6, GCNT3 and MGAT3 as top-upregulated genes in aggressive pancreatic cancer cell lines Capan-1 and HPAF/CD18." (PMID 32203219, 2020).
serous ovarian cancer (1 paper, 2017). "The MS profiling by PGC‐LC also revealed several glycan structural isomers that corresponded to LacdiNAc‐type (GalNAcβ1‐4GlcNAc) motifs that were unique to the serous ovarian cancers and that correlated with elevated gene expression of B4GALNT3 and B4GALNT4 in patients with serous cancer." (PMID 28853212, 2017).
cancer (8 papers, 2014 to 2022). A tumor composed of atypical neoplastic, often pleomorphic cells that invade other tissues. "Of these overlapping genes, several have been implicated in cancer migration/invasion or metastasis, including EPHB6, AGR2, RAB37, CST1, and B4GALNT3." (PMID 34270616, 2021). "We later found that B4GALNT3 expression examined using IHC staining correlates positively with advanced American Joint Committee on Cancer stages, high metastasis rates, and poor survival in colorectal cancer patients." (PMID 27686492, 2016). "Our results suggest that B4GALNT3 plays a role in regulating cancer stem like cell property via the EGF/EGFR pathway." (PMID 25003232, 2014). "Since sphere formation assay is used to enrich the stem-like cells of cancer cells and evaluate their self-renewal capacity, we investigate whether the expression of B4GALNT3 alters in colonospheres compared with adherent cells." (PMID 25003232, 2014). "In this study, we showed that B4GALNT3 regulates cancer cell property via EGFR pathway." (PMID 25003232, 2014). "Furthermore, B4GALNT3 altered LacdiNAc expression of several glycoproteins, these findings indicated that B4GALNT3 might regulate cancer cell properties through other signaling pathways." (PMID 25003232, 2014). "However, the role of B4GALNT3 in cancer stemness remains unclear." (PMID 25003232, 2014). "According to these data, the expression patterns of these genes either increased or decreased in different cancer cell lines, and some of the genes, including MUC20 and B4GALNT3, showed decreased expression in HCC cell lines compared to other cancer cell lines." (PMID 36556285, 2022).
B4GALNT3 also shares sentences with these, for which no sentence is quoted: tumor (4 papers); neuroblastoma (2); prostate carcinoma (2); peritoneal cancer (1); viral infections (1).